IFNGR1 (interferon gamma receptor 1)
Diseases named in the same sentence as IFNGR1 in open-access papers (continued):
Sharing a sentence is not in itself a finding about the gene and the disease.
tumor (continued). "This concern is supported by a recent report showing that in vivo treatment with ruxolitinib did not suppress tumor growth and progression due to the abrogation of antitumor CD8+ T cell function through ruxolitinib-mediated inhibition of JAK1/2-dependent IFNGR1 signaling in T cells." (PMID 38236642, 2024). "This lack of response resulted from cellular defects on IFNγR1 and of JAK proteins and may explain the ability of many tumor cells to evade the immune response." (PMID 29780381, 2018).
infection (104 papers, 2006 to 2026). The state of being infected such as from the introduction of a foreign agent such as serum, vaccine, antigenic substance or organism. "Activates macrophages; IFNγR1 deficiency increases infection risk in mice; enhances IL-6, TNF-α production." (PMID 41268545, 2025). "IFN-γ: activates macrophages; induces IL-6, TNF-α, IL-10 production via JAK-STAT; IFNγR1 deficiency increases infection susceptibility." (PMID 41268545, 2025). "Genetic deficiencies in IFNγR1 compromise host immunity and increase vulnerability to infection since some pathogens have developed mechanisms to inhibit this receptor as a means of immune evasion." (PMID 41268545, 2025). "Consistent with the effects of IFN-γ neutralization, infected Ifngr1−/−Nlrc4−/−Casp11−/− mice experienced greater weight loss burdens than IFN-γ-sufficient Nlrc4−/−Casp11−/− animals 48h after infection." (PMID 40885187, 2025). "The Ifngr1-/- mice exhibited high susceptibility to the virulent Karp strain, with even an extremely low-dose infection (3 FFU) resulting in animal mortality." (PMID 38743761, 2024). "Surprisingly, the presence of the necrotic cell layer around the wound in both Tyk2- and Ifngr1-deficient mice correlates with better fungal containment at the infection site and impaired fungal dissemination to kidneys." (PMID 39622833, 2024). "The clinical manifestations of complete deficiency of IFNGR2 are similar to those of complete IFNGR1 deficiency, and patients present with severe or even fatal infection early in life." (PMID 36569938, 2022). "This demonstrates that i.d. infection of Ifnar1-/-;Ifngr1-/- mice with R. parkeri causes systemic infection and can be used as a model for dissemination from the skin to internal organs." (PMID 34423779, 2021). "Another interesting aspect of our mouse model is that both of our mouse KitW-sh/W-sh Ifnar1−/− Ifngr1−/− and KitW-sh/W-sh Ifnar1−/− Ifngr1+/+ were particularly susceptible to infection by the s.c. infection route, which is the natural route of DENV infection." (PMID 34066286, 2021). "All of the DENV serotypes caused morbidity in KitW-sh/W-sh Ifnar1−/− Ifngr1−/− mice, as indicated by the significantly increased clinical score at various days between day 2 to day 8 post-infection." (PMID 34066286, 2021). "Nevertheless, these findings reveal that i.d. infection can cause lethal disease in Ifnar1-/-;Ifngr1-/- mice with ~10,000-fold lower dose of bacteria than i.v. infection." (PMID 34423779, 2021). "Further, burdens of S. pneumoniae at 4 h after infection (9 days after IAV) were ~50% lower in lungs of IFNγ or IFNGR1-deficient mice than in co-infected control mice." (PMID 32117259, 2020). "Clearly, further studies will be needed to distinguish between the relative contributions of type I versus type II IFN-driven regulation of IFNGR1 in mediating susceptibility to various infections." (PMID 31585982, 2019). "People with one of these disorders—interferon-gamma receptor 1 (IFN- γR1) deficiency—are very susceptible to infections with mycobacteria." (PMID 18232731, 2008). "The IFNGR1 gene mutation may be a potential risk factor for TM infection, and the presence of anti-interferon-γ autoantibodies can aggravate disease symptoms." (PMID 37926601, 2024). "We further examined whether IFNG- and IFNGR1-knockout cell lines show enhanced susceptibility to infection by different types of viruses besides HSV-1." (PMID 35897807, 2022). "Interestingly, weight loss of adult Ifngr1−/− mice within the first 4 d of infection was comparable with that of aged Ifngr1−/− mice." (PMID 36129445, 2022). "However, IFNGR1- and IFNG/IFNGR1-deficient cell lines maintained relatively low levels of IFN-γ-responsive cytokines upon HSV-1 or HCoV-OC43 infection." (PMID 35897807, 2022).
infection (continued). "The loss of age-dependent differences during the first days of infection in Ifngr1−/− mice supports our previous findings obtained by transcriptional profiling, which suggested a relevant contribution of an early and potent IFN-γ response to prevent SARS-CoV-2–induced disease in adult mice." (PMID 36129445, 2022). "We examined if i.v. and i.d. infections of WT and Ifnar1-/-;Ifngr1-/- mice could reveal a pathogenic role for R. parkeri Sca2." (PMID 34423779, 2021). "Levels of IFNGR1 were also diminished at 24 and 36 hours after infection when compared with the 0 hour time point." (PMID 40558091, 2025). "We therefore sought to directly compare the ability of the WT, sca2::Tn, and rickA::Tn strains to colonize internal organs by assessing the bacterial burden in the skin, spleen, liver, lung, and brain following i.d. infection of Ifnar1−/−; Ifngr1−/− DKO mice." (PMID 39819005, 2025). "Strikingly, all Ifngr1−/−Nlrc4−/−Casp11−/− mice reached predefined humane endpoints (e.g., <75% starting body weight, severe signs of morbidity) 72h post-infection, while all Nlrc4−/−Casp11−/− mice survived and regained their initial weight." (PMID 40885187, 2025). "Remarkably, whereas the S.Tm θ strain is unable to colonize lymphoid tissues, the host barriers to infection by this strain are broken in both Myd88−/− and Ifngr1−/− mice, or through co-expression of the spv operon effector SpvB." (PMID 40462990, 2025). "No production of type I IFN was detected, and only moderate amounts of IFNγR1 were observed in response to Delta and BA.1 infection." (PMID 40295859, 2025). "Depletion of Tollip impaired IFNAR1 and IFNGR1 downregulation, most evidently at 24 and 36 hours post-infection." (PMID 40558091, 2025). "In sharp contrast, although AM cell numbers in M. abs-infected Ifngr1−/− mice transiently decreased at early timepoints after infection, they recovered at later timepoints." (PMID 40060898, 2025). "In this case, for unclear reasons, the initial time point showed higher levels of IFNGR1 in the context of infection as compared with uninfected control cells." (PMID 40558091, 2025). "Infection of ALI cultures or Ifngr1-/- mice with mCherry and GFP parasites resulted in cross-fertilization and the formation of "yellow" oocysts, which contain 4 haploid sporozoites that are the product of meiosis." (PMID 38885280, 2024). "Infection of ALI cultures or Ifngr1−/− mice with mCherry and GFP parasites produced “yellow” oocysts generated by cross-fertilization." (PMID 38352509, 2024). "The severe infection and tissue damage of Ifngr1-/- mice were evidenced by the aberrant levels of TP, GLOB and ALB." (PMID 38743761, 2024). "The expression product of IFNGR1 is an interferon-γ receptor, which combines with interferon-γ and participates in the activation of macrophages and anti-infection processes." (PMID 37926601, 2024). "On the other hand, the number of AM was similar in BALB/c versus B6 mice after X31 and/or D39 infection, and B6 Ifngr1-/- mice exhibited comparable AM numbers as B6 WT mice after X31/D39 coinfection." (PMID 37771584, 2023). "Three patients with IFNGR1 deficiency died, of whom 2 had received HSCT, one died of a severe infection 6 months after HSCT, and the other received HSCT and was well after 5 months." (PMID 36569938, 2022). "Lastly, we investigated the molecular mechanism underlying the increased susceptibility to infection by HCoV-OC43 in IFNG- and IFNGR1-knockout cell lines." (PMID 35897807, 2022). "Viral load was much lower in KitW-sh/W-sh Ifnar1−/− Ifngr1−/− mice on day 10 post-infection than day 3, indicating clearance of the virus." (PMID 34066286, 2021). "We next evaluated the role for Sca2 in R. parkeri dissemination by measuring p.f.u. in spleens and livers following i.d. infection of Ifnar1-/-;Ifngr1-/- mice." (PMID 34423779, 2021).
infection (continued). "We observed skin lesion formation at all infectious doses, from 107 to 10 bacteria, suggesting that i.d. infection of Ifnar1-/-;Ifngr1-/- mice elicits lesions with doses similar to what is delivered by tick infestation." (PMID 34423779, 2021). "Variation in IFNGR1 has only been shown to be involved in the development of pathology but it has yet to be tested in a candidate gene study for effect on infection response." (PMID 33659002, 2021). "(a) Survival of Ifnar1-/-;Ifngr1-/- mice upon i.v. infection with 5 × 106 PFU of R. parkeri. n = 7 (WT), 10 (sca2::Tn), and 7 (MC1_RS08740::Tn R. parkeri) individual mice." (PMID 34423779, 2021). "In the first round of infection in Ifngr1−/− mice, all of the animals succumbed by day 15, indicating the tagged line was not attenuated." (PMID 33688009, 2021). "We find that Sca2 is not required for intracellular survival in organs upon i.v. infection of Ifnar1-/-;Ifngr1-/- mice, but rather, is required for dissemination from skin to internal organs and lethality upon i.d. infection." (PMID 34423779, 2021). "The expression of type I (IFNAR1 and IFNAR2) and II (IFNGR1) receptors were suppressed in VSV-infected cells compared to mock-infection." (PMID 34578166, 2021). "In our previous study, IFNGR1 signaling was shown to be involved in adverse pregnancy outcomes during infection with PbNK65." (PMID 34644348, 2021). "In contrast, CW3I514F infection of Ifnar1-/-Ifngr1-/- mice was highly attenuated, with only a ~100-fold increase in viral genomes in MLN and spleen compared to WT mice, and scant virus detected in the brain." (PMID 33705489, 2021). "In some cases, tails of DKO Ifnar1-/-;Ifngr1-/- or single mutant Ifngr1-/- mutant mice became inflamed after i.d. or i.v. infection." (PMID 34423779, 2021). "(d) Weight changes of Ifnar1-/-;Ifngr1-/- mice upon i.d. infection with 107 PFU of R. parkeri. n = 6 (WT) and 8 (sca2::Tn) individual mice." (PMID 34423779, 2021). "Here, deletion of the IFNγR1 subunit had a substantially more profound impact on the acute infection of RMT/MT P. chabaudi infections, than was observed in SBP infections, showing that an early IFNγ response is important in attenuating parasitaemia." (PMID 34532703, 2021). "I.d. infection of Ifnar1-/-;Ifngr1-/- mice with R. parkeri elicits skin lesions that are grossly similar to human eschars." (PMID 34423779, 2021). "Together, the gross pathological analysis and fluorescence-based assay suggest that Sca2 likely does not significantly enhance R. parkeri spread throughout the skin during i.d. infection of Ifnar1-/-;Ifngr1-/- mice." (PMID 34423779, 2021). "For the first time, our findings provide a clue for exploring the effects of IFNG/IFNGR1 SNPs on the prevalence of TB beyond the control of infection acquisition." (PMID 31687049, 2019). "Overall, our data suggest that blocking the ability of type I IFNs to suppress macrophage IFNGR1 restores host resistance to systemic L. monocytogenes infection by improving antimicrobial “M1” activation of monocytes recruited to sites of infection." (PMID 28542482, 2017). "After infection with T. gondii, a lower Ifngr1 mRNA and a higher expression of Tlr4 mRNA were observed in Nox4−/− BMDMs." (PMID 28743960, 2017). "Conversely, the expression of IFNAR1 and IFNGR1 was either unchanged by infection or downregulated with time, respectively, indicative of plasticity in regulating the type I IFN response and a disengagement of the type II IFN response." (PMID 28993767, 2017). "To examine development of protective immunity, we treated matched cohorts of persistently infected or cleared Ifngr1-/- mice with an antimalarial drug approximately 4 months post-infection in order to completely eliminate parasites." (PMID 27583554, 2016). "Throughout infection IDO activity remained at basal levels in lungs of X31-infected IFNγR1-KO mice, relative to basal IDO activity in lungs from uninfected mice (not shown), indicating that IFNγ induced IDO in infected lungs." (PMID 23785507, 2013).
infection (continued). "Despite the increased severity of infection in Ifngr1−/− mice, parasites were controlled in all mice by 40 days post-infection." (PMID 23144737, 2012). "Ifngr1−/− mice were completely susceptible to infection with ROP5 deficient parasites, succumbing in the same time frame as wild type C57BL/6 or Ifngr1−/− mice infected with virulent wild type parasites." (PMID 23144612, 2012). "By day 45 post-infection, C. trachomatis was still detectable in Ifngr1-/- mice but undetectable in wildtype and Irgm1/m3(-/-) mice." (PMID 21731484, 2011). "Conversely, infection for 4 hr markedly reduced the extent of IFNγR2 coprecipitation with IFNγR1 even in IFNγ stimulated condition, while the level of coprecipitated IFNγR2 went below detection level with increasing time of infection." (PMID 21931549, 2011). "Endogenous IFNγR1 distribution was less affected during early (4th) hours of infection, but with increasing severity of infection it was completely delocalized from the raft fractions." (PMID 21931549, 2011). "The results also reveal that, there is a considerable decrease in the percentage of colocalized IFNγR1 with GM1 in the macrophage membrane at 4 hour post LD infection (71%) than the basal condition." (PMID 21931549, 2011). "Ifngr1−/− mice challenged i.v. with 106 CFU of BCG were unable to control the infection: the bacterial load in the spleen increased to 7.4 ± 0.3 (Log10 CFU) by 45 d after infection and exceeded 8 Log10 CFU in dying animals." (PMID 18232731, 2008). "IFN-γ was detected as early as 10 d post-infection and its concentration gradually increased towards a plateau at about 6 ng/ml within six wk of infection in Ifngr1−/− mice, confirming previous observations." (PMID 18232731, 2008). "Deficient animals survived 29 ± 2 weeks (mean ± SD) following challenge with 102 CFU, whereas no mortality was observed in wild-type C57BL/6 control mice (Ifngr1+/+) during 12 mo of follow-up, even after infection with the highest counts of CFU." (PMID 18232731, 2008). "Furthermore, using intradermal infections of Ifnar1−/−; Ifngr1−/− DKO mice, we found that Sca2 contributes to colonization of and spread within internal organs, whereas RickA contributes to eschar formation on the skin." (PMID 39819005, 2025). "We previously showed that sca2::Tn R. parkeri strains are attenuated in lethality and dissemination from the skin to the liver and spleen following i.d. infection of Ifnar1−/−; Ifngr1−/− DKO mice, and our current results extend these findings to the lung and brain." (PMID 39819005, 2025). "Infection experiments revealed that all wild-type C57BL/6 mice survived until day 30 of infection, while all mice deficient in the IFN-γ receptor (Ifngr1-/- mice) succumbed, indicating that TgCatJp5 is a low virulent strain and is eliminated by an IFN-γ-dependent immune response." (PMID 38778039, 2024). "In this study, the authors reported a rare case of endemic, non-HIV, non-immunosuppressive, anti-interferon-γ autoantibodies negative TM infection with IFNGR1 gene mutation." (PMID 37926601, 2024). "In addition, Th2 cytokines including IL-4 and IL-5 were also decreased in Ifngr1-/- mice following infection, suggesting the downregulation of both type 1 and 2 immune responses in the absence of IFN-γ signaling." (PMID 38743761, 2024). "The fatal course of infection occurred in an infant with partial IFNGR1 (Interferon γ Receptor 1 deficiency), in whom the cause of death was CMV(Cytomegalovirus) infection, and in one infant with IL12R (Interleukin 12 subunit 40) deficiency in whom anti-TB therapy was stopped." (PMID 35664873, 2022). "However, the number of bacteria delivered from tick infestation likely varies depending on many factors, and we therefore sought to examine the effects of different doses of R. parkeri upon i.d. infection of Ifnar1-/-;Ifngr1-/- mice." (PMID 34423779, 2021).